CRP (C-reactive protein)
Diseases named in the same sentence as CRP in open-access papers (continued):
Sharing a sentence is not in itself a finding about the gene and the disease.
diabetes (continued). "The diagnostic model with the highest area under the curve (AUC = 0.736, 95% CI: 0.715–0.757) incorporated variables such as age, sex, race, BMI, family PIR, education, drinking, smoking, hypertension, diabetes, CRP, and MLR." (PMID 41316464, 2025). "In the multivariable linear regression model, length of hospital stay was modeled as a function of age, acute presentation severity, comorbidity burden, diabetes, and CRP." (PMID 41517288, 2025). "While we have taken confounders such as maternal age, CRP and pre-BMI into account in our analyses, risk factors for GDM such as socioeconomic status, family history of diabetes, physical activity or weight gain during pregnancy were left out." (PMID 40512705, 2025). "Older adults also tend to exhibit elevated baseline inflammatorymarkers (e.g., IL-6, CRP) and distinct diabetes pathophysiology—primarilydriven by β-cell dysfunction in older populations versus insulinresistance in younger groups." (PMID 41356294, 2025). "They reported that CRP levels correlated positively with BMI, duration of diabetes, and the presence of metabolic syndrome, highlighting the involvement of CRP in atherosclerosis progression." (PMID 40725102, 2025). "First-trimester assessment of biochemical markers, particularly CRP and PPBS, combined with clinical risk factors such as history of PCOS and family history of diabetes, provides a robust and early prediction model for GDM in South Indian women." (PMID 41200603, 2025). "The altered levels of adipokines such as adiponectin and leptin, along with pro-inflammatory markers like CRP and IL-6, underscore the complexity of diabetes etiology in this population." (PMID 41523554, 2025). "This study aimed to investigate the association between CRP/HDL-c and the prevalence of hyperuricemia (HUA) among adults with diabetes or prediabetes." (PMID 40655403, 2025). "MGH contains extensive clinical features, including comorbidities (e.g. hypertension, diabetes, heart and kidney disease), biochemical markers (CRP, D-dimer, LDH), and patient demographics." (PMID 39921901, 2025). "Studies have shown that patients with type 2 diabetes exhibit increased concentrations of C-reactive protein (CRP) and interleukin-6 (IL-6), both of which are associated with a higher risk of diabetes-related complications." (PMID 41030257, 2025). "Given the background information on the association between CRP levels and diabetes, especially T2DM, the primary objective of this study was to examine the relationship between the CTI and diabetes mellitus." (PMID 40988175, 2025). "After adjusting for classical diabetes risk factors, the associations between HS with lower metabolic syndrome (Mets-BMI), hepatic insulin resistance (HOMA-IR), CRP and increased whole body insulin sensitivity (MATSUDA) remained significant." (PMID 41276872, 2025). "These include advanced age, male sex, obesity, cardiovascular disease, diabetes, elevated inflammatory markers (e.g., CRP, ferritin, LDH), lymphopenia, and abnormal coagulation parameters." (PMID 41020217, 2025). "Subgroup analysis, after adjusting for age, sex, body mass index, CRP, creatinine clearance, and diabetes, revealed an interaction between SII and body mass index in the subgroup analysis of SII and all-cause mortality (p < 0.05)." (PMID 40129693, 2025). "Multi-factor Logistic regression analysis showed that diabetes, decreased hemoglobin level, increased serum PAF and IL-17 levels, CRP, were the independent risk factors for intestinal obstruction in patients with radiation enteritis (p < 0.05)." (PMID 40823570, 2025). "The evaluation of markers, such as interleukin-1, IL-6, CRP and TNF-α, is essential for investigating the association between periodontitis and diabetes mellitus." (PMID 40667952, 2025). "This study aimed to examine the association between C-reactive protein (CRP) levels and the severity of DFI in patients with diabetes." (PMID 40373091, 2025).
diabetes (continued). "The initial presentation of our patient, with a high HbA1c level of 12.9% and elevated CRP, indicates poor diabetes control and systemic inflammation—both contributing factors to the development of Charcot neuroarthropathy." (PMID 40093938, 2025). "Compared with the normal ABI group, patients in the low ABI group were older, had lower BMI, more diabetes and cerebrovascular disease, and higher CRP levels." (PMID 40786290, 2025). "Covariates included age, sex, energy intake, living area, education level, income, smoking status, physical activity, BMI, hypertension, diabetes, use of dietary supplements, and Hs-CRP level." (PMID 41383345, 2025). "Cancer, hypertension, myocardial infarction, stroke, and diabetes were more common among persons with higher serum levels of CRP (all p < 0.0001)." (PMID 40023976, 2025). "Non-response odds were higher with CAUTI (aOR 1.9, 95% CI 1.1–3.2), longer time-to-effective therapy per 6 h (aOR 1.5, 1.2–2.0), baseline CRP per 20 mg/L (aOR 1.3, 1.0–1.7), and diabetes (aOR 1.8, 1.0–3.3)." (PMID 41462885, 2025). "Melatonin supplementation in patients with type 2 diabetes mellitus led to significant improvement in cognitive function as assessed by the MoCA score, along with reductions in HbA1C and CRP levels." (PMID 41281014, 2025). "In our model, we maintained an EPV value of 6.5 with two variables: diagnosis of diabetes and preoperative CRP level." (PMID 40363957, 2025). "PVAT-derived CRP has increased levels during obesity and diabetes mellitus and has been shown to promote neointimal hyperplasia after endovascular injury in HFD mice." (PMID 40137085, 2025). "STEMI patients with known diabetes were older, had more frequently hypertension, more often low left ventricular EF values, higher admission glucose, HbA1c, and peak CRP values." (PMID 39962379, 2025). "This association was observed in patients with normal baseline renal function and was independent of conventional risk factors for kidney and cardiovascular diseases, including baseline eGFR, age, race, diabetes, hypertension, and CRP levels." (PMID 41008604, 2025). "To further investigate the association between SII and cancer mortality, we explored a number of factors that influence the association with cancer mortality, such as female, age, higher body mass index, higher CRP, creatinine clearance, and diabetes." (PMID 40129693, 2025). "A comparison of two study groups according to tested variables in the univariate analysis revealed that preoperative C-reactive protein (CRP) levels and history of diabetes were significantly associated with PJI (p < 0.05)." (PMID 40363957, 2025). "The covariates include age, C-reactive protein, urinary creatinine, education level, race, marital status, ratio of family income to poverty, BMI, hypertension, high cholesterol level, diabetes, drinking status, and serum cotinine." (PMID 40783521, 2025). "Models were adjusted for age, sex, diabetes, BMI, smoking status, estimated glomerular filtration rate, serum albumin, CRP, calcium, phosphate, and statin use." (PMID 40786290, 2025). "The elevation observed in our study population with concurrent periodontitis and diabetes mellitus is particularly concerning given the established relationship between hs-CRP levels and future diabetes." (PMID 41153725, 2025). "Age,race,education level,marital status,PIR,smoking status,alcohol consumption, HB,CRP,TC, Diabetes, hypertension, kidney failure, CVD were adjusted." (PMID 40378149, 2025). "In her PhD dissertation, Fudalej observed that among patients with PC and diabetes mellitus, a CRP level ≤ 5 mg/L was the strongest predictor of survival." (PMID 40361411, 2025). "Model 1 = adjusted for age, sex, schooling, hypertension, diabetes, cardiovascular disease, stroke, smoke, alcohol, physical activity, cognitive performance, and BMI; Model 2 = Model 1 + C-reactive protein and albumin." (PMID 40929405, 2025).
diabetes (continued). "These include subjective dyspnea and/or objective respiratory effort, respiratory distress, stridor, elevated C-reactive protein, older age, body mass index greater than 25 kg/m2, and a history of diabetes mellitus." (PMID 41146331, 2025). "C-reactive protein (CRP), an acute-phase reactant synthesized in response to inflammation, has emerged as a potential marker of disease severity in diabetes and its complications." (PMID 41367458, 2025). "Previous real-world prospective cohorts have demonstrated that co-exposure to elevated hs-CRP and high AIP is associated with an increased risk of diabetes." (PMID 40842496, 2025). "Its associations with immunological and biochemical parameters, including ferritin, CRP, and ALP, as well as with demographic and clinical features such as sex and diabetes mellitus, reinforce its potential as a monitoring and risk stratification tool." (PMID 41171774, 2025). "This population-based study provides novel evidence for an association between the CRP/HDL-c ratio and the risk of HUA in patients with diabetes or prediabetes." (PMID 40655403, 2025). "Variables were excluded in the following order: antibiotic use prior to admission, alcohol consumption, hypertension, diabetes mellitus and CRP at first day." (PMID 41438567, 2025). "The Women’s Health Study (2001) identified CRP as a powerful independent predictor of incident diabetes in over 27,000 women." (PMID 40725102, 2025). "Older age, systemic inflammatory markers (NLRs, ESR, CRP), multispace involvement and comorbidities like diabetes are significant predictors." (PMID 39859111, 2025). "Logistic regression indicated that CAUTI was associated with 2.3-fold higher odds of extended hospitalization (95% CI: 1.2–4.4, p = 0.02), adjusting for age, diabetes, and CRP levels." (PMID 40431302, 2025). "CRP has been consistently shown to correlate with a variety of inflammatory conditions, including metabolic syndrome, cardiovascular disease, and diabetes, making it a valuable biomarker for clinical practice." (PMID 41245414, 2025). "Participants in the highest eGDR tertile were generally younger, had lower BMI and CRP, and exhibited a lower prevalence of dyslipidemia, diabetes, heart disease, and stroke compared to those in the lowest tertile." (PMID 39975601, 2025). "Sitagliptin effect on diabetes-associated inflammation was assessed by measuring cardiac levels of IL-1β, TNF-α, and CRP, which were significantly elevated (p ≤ 0.001) in diabetic rats." (PMID 40867548, 2025). "Participants with higher TyG index were found to be older, with a higher level of WBC, CRP and a higher prevalence of hypertension and diabetes (P < 0.001)." (PMID 39915784, 2025). "The primary risk factors for CAS include age, smoking, hypertension, low-density lipoprotein cholesterol (LDL-C), diabetes, and high-sensitivity C-reactive protein (Hs-CRP) levels." (PMID 40894481, 2025). "Increased levels of CRP and IL-6 are present in all diabetes subtypes compared to their control groups." (PMID 40022072, 2025). "Fasting insulin, C-reactive protein, and fasting glucose—typically elevated in diabetes—also showed decreases, likely reflecting vitamin D’s protective effects on pancreatic β cells." (PMID 41010515, 2025). "Previous studies have identified several clinical indicators, such as age, pathology, history of diabetes, and initial T stage, along with biochemical markers including hemoglobin, albumin, and C-reactive protein, as independent predictors of PRNN." (PMID 41023922, 2025). "Multivariable regression identified older age, longer disease duration, higher PASI scores, hypertension, diabetes, and CRP as independent predictors of CVD." (PMID 41112228, 2025). "Among the markers analyzed, CRP demonstrated the strongest predictive value for diabetes, followed by IL-6." (PMID 41523554, 2025).
diabetes (continued). "Biomarkers, including lipid profiles, diabetes indexes, and inflammatory markers such as C-reactive protein, were incorporated in 3 studies (23.1%) to enhance PRS models by providing molecular-level insights into the pathways involved in CVD." (PMID 40579068, 2025). "Although researchers have not fully understood the exact relationship between CRP levels and the development of diabetes, numerous studies have demonstrated a significant correlation between elevated CRP levels and DM." (PMID 40893911, 2025). "The study evaluated the association between the hs-CRP/HDL ratio and the risk of developing type 2 diabetes mellitus (T2DM) employing multivariate logistic regression, subgroup analyses, smooth curve fitting, and threshold effect analysis." (PMID 40123888, 2025). "Across CRP strata, patients with higher CRP levels tended to be slightly older and exhibited a greater prevalence of hypertension, diabetes, and smoking history, suggesting a higher inflammatory and cardiovascular risk burden." (PMID 41200636, 2025). "Patients in the CI-AKI group were older, had higher levels of fasting blood glucose (FBG), caIMR, CRP, hs-TnT, and NT-proBNP, and a higher prevalence of diabetes and left anterior descending artery (LAD) involvement." (PMID 40376146, 2025). "Adjusted by age, sex (for the overall population), energy intake, living area, education level, income, smoking status, physical activity, BMI, hypertension, diabetes, use of dietary supplements, and Hs-CRP level." (PMID 41383345, 2025). "These included smoking, hypertension, diabetes mellitus, alcohol use, chronic obstructive pulmonary disease (COPD), vitamin D deficiency, reduced renal function (eGFR < 60), elevated C-reactive protein (CRP ≥ 10), and older age (≥50 years)." (PMID 40722700, 2025). "Periodontal therapy appears to significantly reduce HbA1c and CRP levels over short-term periods in diabetic patients, suggesting potential as a beneficial adjunct to diabetes management." (PMID 40070580, 2025). "This process is distinct from other diabetes-related problems, such as retinopathy and nephropathy, in which interleukin-6 (IL-6) and C-reactive protein (CRP) play a more prominent role." (PMID 40149566, 2025). "In previous studies of CHF and diabetes patients, depressive symptoms were associated with higher levels of the proinflammatory cytokines TNF‐α, IL‐6, and CRP, and lower levels of the anti‐inflammatory cytokines IL‐10 and ADPN." (PMID 40700022, 2025). "Women in Q1 had a higher degree of inflammation (p-CRP; p < 0.001), a larger proportion had diabetes (Q1 18% vs. Q5 3%; p for trend < 0.001) and polypharmacy (Q1 29% vs. Q5 17%; p for trend < 0.001)." (PMID 41364151, 2025). "The survival group had lower rates of hypertension, diabetes, and chronic kidney disease; was significantly younger; had shorter low-flow times; and exhibited lower levels of CRP, lactic acid, and INR, obtained on the hospital admission." (PMID 40265189, 2025). "The PAD group had a higher prevalence of diabetes mellitus (p = 0.026), elevated serum C-reactive protein (CRP) levels (p < 0.001) and increased PCS levels (p = 0.002) than the normal ABI group." (PMID 40361914, 2025). "Our data advocate for integrated care models incorporating depression screening and CRP monitoring in arthritis patients, particularly those with diabetes." (PMID 40904459, 2025). "Second, adjustments for key covariates such as BMI, diabetes status, smoking status, fasting glucose levels, and CRP levels were performed." (PMID 40731833, 2025). "Participants who developed diabetes during follow-up had a lower mean vitamin D level (17 ± 8 vs. 20 ± 8 ng/mL) and a higher mean CRP level (4.01 ± 5.27 vs. 2.36 ± 4.11 mg/L) than those who did not." (PMID 39662157, 2025).
diabetes (continued). "In a clinical study utilizing proteomics-supported biomarker models, OPN emerged as a significant predictor of procedural AKI, along with diabetes history, the blood urea nitrogen-to-creatinine ratio, C-reactive protein, and additional factors." (PMID 40243457, 2025). "This study also found that diabetes patients have higher levels of CRP and albumin than healthy individuals." (PMID 40792303, 2025). "Model 4 maintains the OR at 3.28 even after adjusting for lifestyle and clinical variables, including smoking, alcohol consumption, diabetes, UA, and CRP levels, confirming the steady impact of these factors." (PMID 40760618, 2025). "CRP serves as a sensitive biomarker for various inflammatory conditions, including diabetes, obesity, and cardiovascular disease, while elevated levels of CRP and erythrocyte sedimentation collectively indicate potential infection." (PMID 40574084, 2025). "Many studies also described a high burden of comorbidities, such as diabetes mellitus, chronic kidney disease, and hazardous alcohol use—factors that can influence inflammatory markers like CRP." (PMID 41010302, 2025). "As expected, the diabetes cohort presented higher levels of HbA1c and increased CRP levels in both the infected and uninfected groups." (PMID 40962954, 2025). "Based on a simple integer score of hs-cTnT, NT-proBNP, hs-CRP, LVH, it can effectively stratify the heart failure risk in patients with diabetes and prediabetes." (PMID 40873950, 2025). "Thus, exploring associations between AAM and CRP, fasting insulin, and fasting glucose on a nationally representative sample with a wide age range of both pre- and postmenopausal women to elucidate possible pathways for the increased risk in diabetes in those with earlier AAM is warranted." (PMID 38912813, 2025). "Older age, male sex, elevated CRP, and diabetes are predictors of adverse outcomes in both patients with cystitis and PN." (PMID 40262850, 2025). "In people with diabetes, CRP levels are often elevated, indicating the presence of chronic low‐grade inflammation, which is a risk factor for cardiovascular disease." (PMID 39355932, 2025). "Microalbuminuria was significantly associated with diabetes (p = 0.033), individuals living with HIV (p = 0.035), and high-sensitivity C-reactive protein (Hs-CRP) (p = 0.007) in univariate analysis." (PMID 40658688, 2025). "Hypertension and diabetes were more prevalent in Group D, while serum high-sensitivity CRP levels were elevated in Groups C and D." (PMID 40636778, 2025). "This demonstrates that higher baseline hs-CRP levels, along with diabetes, are predictive of microalbuminuria progression." (PMID 40658688, 2025). "Univariate logistic regression analysis showed that IBI > 18.89, NLR, lymphocyte count, LVEF, eGFR, CRP, FBG, Killip class >2, IRA- LAD, diabetes, and NT-proBNP were associated with the occurrence of CI-AKI during hospitalization (P < 0.05)." (PMID 40182426, 2025). "It has also been shown that serum HbA1c levels were positively correlated with CRP levels and periodontal parameters in patients before diabetes onset." (PMID 40260278, 2025). "For systemic diseases such as OA, diabetes and cancer that often had chronic low-grade inflammation, CRP, fibrinogen and serum amyloid A (SAA) are often elevated." (PMID 40943351, 2025). "Blood results indicated slightly elevated creatinine kinase, C-reactive protein, and erythrocyte sedimentation rate levels, and poor diabetes control." (PMID 40922886, 2025). "It resulted in a significant association between all-cause mortality and older age, male gender, more severe carotidal VC, increased CRP, low albumin, presence of diabetes, and cardiovascular diseases." (PMID 40136613, 2025). "Specifically, FIB-4 was related to hypertension and hyperlipidemia, CRP/Alb to diabetes, and TG/HDL and TG/Glucose to BMI, reflecting their complementary value in assessing both fibrotic and metabolic components of obesity." (PMID 41302334, 2025).